Y_RNA (Y RNA )
Gene: Miscellaneous RNA gene on chromosome 7 (156,186,122 to 156,186,223, reverse strand). Ensembl gene ENSG00000207061.
Homologues: Orthologues: guinea pig Y_RNA (97% identical), chimpanzee Y_RNA (95% identical), macaque Y_RNA (94% identical). Paralogues in human: Y_RNA (95% identical), RNY3 (94% identical), RNY3P1 (94% identical), Y_RNA (94% identical), Y_RNA (93% identical), Y_RNA (92% identical), Y_RNA (91% identical), Y_RNA (90% identical), RNY3P11 (89% identical), RNY3P14 (89% identical), Y_RNA (89% identical), RNY3P16 (88% identical), and 101 more.